RN7SKP136 (RN7SK pseudogene 136)
Gene: Miscellaneous RNA gene on chromosome 4 (177,181,442 to 177,181,741, forward strand). Ensembl gene ENSG00000222859.
Homologues: Orthologues: guinea pig 7SK (42% identical). Paralogues in human: RN7SKP79 (65% identical), RN7SKP77 (65% identical), RN7SKP124 (64% identical), RN7SKP170 (64% identical), 7SK (64% identical), RN7SKP249 (64% identical), RN7SKP180 (63% identical), RN7SKP133 (63% identical), RN7SKP137 (63% identical), RN7SKP162 (63% identical), RN7SKP294 (63% identical), RN7SKP127 (62% identical), and 284 more.